BOD1L2 (biorientation of chromosomes in cell division 1 like 2)
Description:
May play a role in proper chromosome biorientation through the detection or correction of syntelic attachments in mitotic spindles.
Synonyms: BOD1P; FAM44C; MGC33608
Tractability: No criterion of Open Targets' tractability assessment is met for any kind of drug.
Gene: Protein-coding gene on chromosome 18 (57,147,087 to 57,150,410, forward strand). Ensembl gene ENSG00000228075.
Subcellular location: Cytoplasm, cytoskeleton, microtubule organizing center, centrosome; Chromosome, centromere, kinetochore
Gene Ontology:
Molecular function: protein binding
Cellular component: centrosome
Genetic constraint (gnomAD): Loss-of-function variants: 9 observed, 8.04 expected, observed/expected ratio (o/e) 1.12, 90% interval 0.67 to 1.8. That is too few expected variants to judge how well the gene tolerates losing a copy. Missense variants: 184 observed, 184.18 expected, observed/expected ratio (o/e) 1, 90% interval 0.88 to 1.13. Synonymous variants: 83 observed, 71.32 expected, observed/expected ratio (o/e) 1.16, 90% interval 0.97 to 1.4.
Homologues: Orthologues: chimpanzee BOD1L2 (99% identical), dog BOD1 (83% identical), mouse Bod1 (81% identical), rat Bod1 (81% identical), tropical clawed frog bod1 (66% identical). Paralogues in human: BOD1 (86% identical), BOD1L1 (52% identical).
Diseases named in the same sentence as BOD1L2 in open-access papers:
BOD1L2 is named in the same sentence as 4 diseases in open-access papers, as found by Europe PMC text mining. Sharing a sentence is not in itself a finding about the gene and the disease. The quoted sentences say what the papers report.
Klinefelter syndrome (1 paper, 2023). A sex chromosome disorder caused by the presence of an extra X chromosome in the male karyotype. "Moreover, BOD1L2, C1orf194, and KRTCAP2 are found to indicate testicular spermatogenic capacity in a variety of testicular diseases, such as Y‐chromosome microdeletions and Klinefelter syndrome." (PMID 37083227, 2023).
cancer (1 paper, 2020). A tumor composed of atypical neoplastic, often pleomorphic cells that invade other tissues. "Six of these genes have been reported to be associated with cancers, including LOC284933, BOD1L2, MIR7515, ZNF729 and ZNF479, and MKL1." (PMID 32414326, 2020).
BOD1L2 also shares sentences with these, for which no sentence is quoted: testicular diseases (1 paper); tumor (1).